CBFB (core-binding factor subunit beta)
Diseases named in the same sentence as CBFB in open-access papers (continued):
Sharing a sentence is not in itself a finding about the gene and the disease.
breast carcinoma (continued). "We used an online database to analyze the expression and prognostic value of core binding factor subunit β (CBFB) and oxidative stress–related targets in patients with breast cancer." (PMID 35903297, 2022). "Given these contradictory roles of CBFB in breast cancer, we investigated the role of CBFB in breast cancer development and progression." (PMID 35903297, 2022). "The Cancer Genome Atlas (TCGA) cohort exhibited abnormal CBFB expression in breast cancer and TNBC tissues." (PMID 35903297, 2022). "Accordingly, decreased OPN and Runx2 expression following CBFB-knockdown suggests a potential role for CBFB in the treatment of bone metastasis in patients with breast cancer." (PMID 35903297, 2022). "By contrast, in breast cancer, CBFB overexpression suppresses the NOTCH oncogenic signaling pathway and migration ability of the breast cancer cells." (PMID 35903297, 2022). "We observed that the exosomes from patients with bone metastatic breast cancer had markedly higher CBFB expression than those from healthy controls and patients with primary breast cancer." (PMID 35903297, 2022). "Using an independent breast cancer dataset in TCGA (The Cancer Genome Atlas), we identified nine genes that genetically interact with CBFB." (PMID 33945523, 2021). "We applied an algorithm that calculates the genetic interactions of CBFB and other cancer genes in breast cancer." (PMID 33945523, 2021). "The main goal of this study is to further elucidate the mechanisms of the tumor suppressive functions of CBFB in breast cancer." (PMID 33945523, 2021). "Based on these assumptions, we calculated the genetic interaction between mutations in the CBFB gene and other highly mutated genes in the METABRIC (Molecular Taxonomy of Breast Cancer International Consortium) dataset." (PMID 33945523, 2021). "Previously, we showed that CBFB is a dual-function protein that regulates both translation and transcription in breast cancer." (PMID 33945523, 2021). "Here we show, using MDA-MB-231 cells as a model, that the plasticity of at least some metastatic breast cancer cells is dependent on the transcriptional co-regulator CBFβ." (PMID 32005976, 2020). "Mutations in CBFβ are amongst the most frequently reported for breast cancer tumours, suggesting a tumour suppressor role for CBFβ in ER+ breast cancer." (PMID 32005976, 2020). "Infrequent mutations in CBFB, MAP3K4 and ZNF384 are enriched in Stage I, together with classic breast cancer gene AKT1." (PMID 33087126, 2020). "In this study, we have shown that the RUNX co-regulator CBFβ is essential to drive MDA-MB-231 breast cancer cells through EMT." (PMID 32005976, 2020). "We have previously shown that depletion of CBFβ in metastatic MDA-MB-231 breast cancer cells inhibits their ability to migrate." (PMID 32005976, 2020). "In this study, we set out to elucidate the function of CBFB in breast cancer and unexpectedly discover an unexpected role of CBFB in translation regulation." (PMID 31061501, 2019). "We propose that breast cancer cells evade translation and transcription surveillance simultaneously by CBFB downregulation." (PMID 31061501, 2019).
breast carcinoma (continued). "To study the function of CBFB in breast cancer, we generated CBFB knockout (KO) cell lines from MCF10A cells, a non-tumorigenic human mammary epithelial cell line, using the clustered regularly-interspaced short palindromic repeats (CRISPR)-Cas9 technology." (PMID 31061501, 2019). "Binding of hnRNPK and CBFB to RUNX1 mRNA was also detected in several other breast cancer cell lines, indicating that binding of hnRNPK and CBFB to RUNX1 mRNA is a general mechanism." (PMID 31061501, 2019). "In luminal-type breast cancer cell lines (MCF7, T47D, BT474, and ZR751), RUNX1 levels were almost undetectable and CBFB levels were lower than in triple negative and basal-like types of breast cancer cell lines." (PMID 31061501, 2019). "The CBFB mutations were found to be accompanied by deletions of the gene encoding its binding partner, RUNX1, in some breast cancers." (PMID 26870154, 2015). "RUNX1, a common partner of CBFB in hematopoietic cells, was, also, deleted in some breast cancer patients." (PMID 26561834, 2015). "To this end we established that Runx2/CBFβ regulates the expression of genes that mediate both the activation of osteoclasts and the inhibition of osteoblasts by metastatic breast cancer cells." (PMID 22032690, 2011). "The aim of this study was to identify genes regulated by Runx2/CBFβ that contribute to the ability of metastatic breast cancer cells to modulate the activity of bone cells." (PMID 22032690, 2011). "We have previously demonstrated that Runx2 requires the co-activator core binding factor beta (CBFβ) to regulate gene expression in breast cancer cells." (PMID 22032690, 2011). "This study demonstrates that Runx2 and CBFβ are required for the expression of genes that mediate the ability of metastatic breast cancer cells to directly modulate both osteoclast and osteoblast function." (PMID 22032690, 2011). "We also show that Runx2/CBFβ regulates expression of the Wnt antagonist sclerostin and thus reveal a mechanism by which Runx2 mediates osteoblast inhibition by breast cancer cells." (PMID 22032690, 2011). "Runx2 and CBFβ are required for the expression of genes that mediate the ability of metastatic breast cancer cells to directly modulate both osteoclast (GM-CSF, IL-11) and osteoblast (sclerostin) function." (PMID 22032690, 2011). "This analysis identified the osteoclastogenic cytokines IL-11 and granulocyte-macrophage colony-stimulating factor (GM-CSF) as new Runx2/CBFβ targets in breast cancer cells." (PMID 22032690, 2011). "We also identified the osteoclast activators IL-11 and granulocyte-macrophage colony-stimulating factor (GM-CSF) as new target genes of Runx2/CBFβ in metastatic breast cancer cells." (PMID 22032690, 2011). "Here we demonstrate that CBFβ is expressed in metastatic breast cancer cells and that it is essential for cell invasion." (PMID 20591170, 2010). "As master regulators in both development and disease, the RUNX/CBFβ complex holds multifaceted attributes that need to be unraveled further to understand the mechanisms behind their complex and context dependent role in breast cancer." (PMID 36831308, 2023). "In addition, CBFB is also shown to bind to a large pool of mRNAs and enhance translation in breast cancer cells." (PMID 37454130, 2023). "We review how alterations to RUNX/CBFβ function contextually ascribe to breast cancer subtypes and discuss how the in vitro analyses and mouse model systems have contributed to our current understanding of these proteins in the pathogenesis of this complex set of diseases." (PMID 36831308, 2023). "An independent study also reported two RUNX1 mutations and four mutations in CBFB in ER+ luminal tumors, while Nik-Zainal and colleagues showed that both RUNX1 and CBFB were in the top 50 of 93 genes at risk of acquiring driver mutations in breast cancers." (PMID 36831308, 2023).
breast carcinoma (continued). "This is also supported by data from the METABRIC study, where 14% of primary breast cancer samples were found to harbor alterations in CBFB, while 11%, 5% and 4% of patient samples possessed various categories of genetic alterations in RUNX1, RUNX2 and RUNX3, respectively." (PMID 36831308, 2023). "CBFB/RUNX1 axis is reported to function as a tumor suppressor in breast cancer." (PMID 37454130, 2023). "Breast cancer cells avoid translation and transcriptional surveillance by downregulating CBFB." (PMID 37187521, 2023). "Interestingly, circulating exosomes derived from the serum of breast cancer patients with bone metastasis demonstrated significantly higher levels of CBFB compared to those derived from healthy patients or patients with no observable metastasis." (PMID 36831308, 2023). "Additionally, these results highlighted that CBFB undergoes varying alterations depending on the breast cancer subtype in a similar way to that for RUNX1." (PMID 36831308, 2023). "We identified CBFB as a cancer driver in most subgroups in our breast cancer patients." (PMID 37454130, 2023). "However, another study reported that CBFB upregulation is required to maintain the invasive ability of breast cancer cells." (PMID 35903297, 2022). "According to recent studies, the circulating exosomes in breast cancer patients with bone metastasis are rich in core binding factor subunit β (CBFB), which regulates bone metastasis markers, changes endogenous oxidative stress levels, and promotes bone metastasis in breast cancer patients." (PMID 36497209, 2022). "Thus, to explore the probable role of CBFB in breast cancer metastasis, we assessed CBFB expression in primary and metastatic (the lung, brain, and bone) breast cancer tissues." (PMID 35903297, 2022). "Circulating exosomes from patients with breast cancer metastasis to the bone were rich in CBFB." (PMID 35903297, 2022). "Moreover, we examined the effects of tumor-derived CBFB-rich exosomes on the acquisition of CAF-like phenotypes and the associated metastatic and oxidative stress potential of breast cancer cells." (PMID 35903297, 2022). "CBFB may thus serve as a novel therapeutic target for bone metastasis in patients with breast cancer." (PMID 35903297, 2022). "Similarly, expression data from the cancer cell line encyclopedia indicated that CBFB expression in primary breast cancer cell lines was significantly lower than that in the metastatic breast cancer cell lines." (PMID 35903297, 2022). "Considering that tumor-derived exosomes may promote breast cancer progression, we investigated their roles in promoting bone metastasis and the contribution of altered exosomal CBFB levels to these processes." (PMID 35903297, 2022). "Indeed, a role for CBFB in the suppression of breast cancer has recently emerged, and it has been reported that nuclear CBFB/RUNX1 complex represses the oncogenic NOTCH signaling pathway in breast cancer." (PMID 33808143, 2021). "It is also unknown whether the CBFB/RUNX1 axis cooperates with different pathways to suppress breast cancer." (PMID 33945523, 2021). "Our previous study found that CBFB suppresses breast cancer partially through NOTCH3 repression." (PMID 33945523, 2021). "Indeed, we have recently discovered a novel function for CBFB in translation regulation in breast cancer." (PMID 33945523, 2021). "CBFB is an emerging tumor suppressor in human breast cancer." (PMID 33945523, 2021).
breast carcinoma (continued). "Therefore, the tumor suppressive function of CBFB in breast cancer includes several mechanisms, TAp73 activation, NOTCH3 repression, and other yet unidentified genes or signaling pathways." (PMID 33945523, 2021). "Emerging evidence suggests that CBFB is a tumor suppressor in breast cancer." (PMID 33945523, 2021). "Importantly, both the cytoplasmic and nuclear functions of CBFB are critical for suppressing breast cancer." (PMID 31061501, 2019). "No mutation was found, implying that in addition to gene mutations, other unknown mechanisms could lead to the downregulation of CBFB protein in breast cancer." (PMID 31061501, 2019). "We then examined whether overexpression of CBFB in breast cancer cells decreases the tumorigenic ability of these cells." (PMID 31061501, 2019). "Thus, our data reveal an unexpected function of CBFB in translation regulation and propose that breast cancer cells evade translation and transcription surveillance simultaneously through downregulating CBFB." (PMID 31061501, 2019). "Thus, the canonical role of CBFB in transcription regulation is also critical for breast cancer suppression." (PMID 31061501, 2019). "We chose RUNX1 and not RUNX2, since RUNX1 together with its binding partner CBFb has recently been discovered to be mutated ~ 4–6% in breast cancers; suggesting its tumor suppressor function in this context." (PMID 29581836, 2018). "CBFβ stimulates DNA-binding of the Runt domain, and is essential for most of the known functions of Runx2, including activation of Runx2-regulated genes in breast cancer cells." (PMID 22032690, 2011). "However, it is not known if the increased expression of Runx2 observed in metastatic breast cancer cells is sufficient to regulate gene expression independently of CBFβ." (PMID 20591170, 2010). "The Runx2/CBFβ interaction might therefore represent a viable therapeutic target in metastatic breast cancer." (PMID 20591170, 2010). "Thus, we have demonstrated, using two independent RNA interference methods that CBFβ contributes to the invasive capacity of metastatic breast cancer cells." (PMID 20591170, 2010). "Such compounds may also be able to disrupt the Runx2/CBFβ interaction in metastatic breast cancer cells." (PMID 20591170, 2010). "CBFβ is expressed in metastatic breast cancer cells and is essential for cell invasion." (PMID 20591170, 2010). "Our results revealed that CBFB may promote bone metastasis in patients with breast cancer." (PMID 35903297, 2022). "Notably, the core-binding factor β subunit (CBFB) plays various critical roles in breast cancer." (PMID 35903297, 2022). "However, NOTCH3 overexpression does not fully recapitulate the effect of CBFB loss-of-function in breast cancer, suggesting that other mechanism(s) also contribute to the tumor suppressive function of CBFB." (PMID 33945523, 2021). "In an in vitro 3D model of basal-like breast cancer, use of the RUNX/CBFβ inhibitor was shown to exert a striking growth-inhibitory effect with almost complete suppression of cell survival and colony formation." (PMID 36831308, 2023). "In contrast to TNBC, RUNX1 and CBFβ have been described as tumor suppressor genes involved in reduced tumor growth and impaired EMT and CSC generation in ER+ breast cancer." (PMID 36766786, 2023). "RUNX2 with CBFβ has been deemed critical for the expression of Osteopontin/IBSP, IL11 and GM-CSF/CFS2 in metastatic breast cancer cells." (PMID 36831308, 2023). "Other known driver genes that weren't identified by the pan-cancer analysis were identified, such as CBFB, CDH1, PTEN in breast cancer and APOB in the liver." (PMID 34997044, 2022). "Since CBFβ forms functional complexes with all RUNX transcription factors, it is essential to establish its role in breast cancer metastasis." (PMID 32005976, 2020). "We therefore compared the 3D morphology of wild-type metastatic breast cancer cells, MDA-MB-231, with MDA-MB-231 cells depleted of CBFβ." (PMID 32005976, 2020).
breast carcinoma (continued). "Since CBFβ facilitates the function of all three RUNX transcription factors, establishing its role in determining the phenotype of breast cancer cells is essential." (PMID 32005976, 2020). "Several lines of evidence support the notion that CBFB and RUNX1 are tumor suppressors in breast cancer." (PMID 31061501, 2019). "In luminal-type breast cancer cell lines, the levels of CBFB were lower compared to MCF10A, MCF12A, and triple negative/basal type breast cancer cell lines." (PMID 31061501, 2019). "However, the CBFB gene is not mutated in these breast cancer cell lines, suggesting that downregulation of CBFB could be through either gene mutation, as shown by whole-genome sequencing studies, or other mechanisms." (PMID 31061501, 2019). "Using human breast tumor microarray, we found that CBFB and RUNX1 levels were significantly lower in breast cancer tissues compared to normal breast tissues while NOTCH3 levels were the opposite." (PMID 31061501, 2019). "This notion is based on the hypothesis that DDR1 and CBFβ operate within the same pathway as RUNX1, contributing to cellular differentiation and structural stability in breast cancer." (PMID 40614729, 2025). "CBFβ is crucial for the operation and function of all three RUNX proteins, and it is becoming apparent that it also plays an important role in cancer etiology, particularly in breast cancer." (PMID 36831308, 2023). "Therefore, breast cancer cells expressing RUNX2 and CBFβ can exploit the various growth factors involved in the homeostasis of bone formation to allow tumor cell mediated osteoclastogenesis and growth of metastatic cells in this environment." (PMID 36831308, 2023). "The nuclear CBFB/RUNX1 complex transcriptionally represses the oncogenic NOTCH signalling pathway in breast cancer." (PMID 37187521, 2023). "CBFβ Inhibitor has been shown to alter the ability of RUNX1 to bind to target genes and alter their expression, thereby inhibiting the growth of leukemia and breast cancer cell lines." (PMID 35458567, 2022). "Finally, small molecule inhibitors that inhibit the interaction between CBFβ and RUNX have been shown to inhibit colony formation in a basal-like breast cancer cell line." (PMID 32005976, 2020). "Finally, downregulation of CBFB and RUNX1 are found in several breast cancer cell lines and human breast cancer tissues." (PMID 31061501, 2019). "We noted a significant reduction of RUNX1 in the luminal-type but not the triple negative type breast cancer cells compared to normal cells while the reduction of CBFB was modest." (PMID 31061501, 2019). "Together, our data demonstrate that CBFβ is essential for invasion of metastatic breast cancer cells and that the expression level of Runx2 is not sufficient to overcome the requirement for CBFβ, at least at a subset of Runx2-target genes." (PMID 20591170, 2010). "Indeed, previous studies have shown that RUNX1 suppresses development of ER+ luminal breast cancer but it is not known how CBFβ contributes in this context." (PMID 32005976, 2020). "Furthermore, nuclear CBFB/RUNX1 complex transcriptionally represses the oncogenic NOTCH signaling pathway in breast cancer." (PMID 31061501, 2019). "Since Runx2 is overexpressed in metastatic breast cancer cells, and there are no reports of CBFβ expression in breast cells, we sought to determine whether Runx2 function in these cells was dependent on CBFβ." (PMID 20591170, 2010). "CBFβ is therefore expressed in both metastatic and non-metastatic breast cancer cell lines." (PMID 20591170, 2010). "Thus, wehypothesized that RUNX1, together with CBFβ, might play a key role in mammaryepithelial cell (MEC) lineage determination as a master regulatory TF and that the lossof this normal function might contribute to breast cancer development." (PMID 25415051, 2014). "Indeed, it is not known if CBFβ is expressed in metastatic breast cancer cells." (PMID 20591170, 2010).